APOE (apolipoprotein E)
Diseases named in the same sentence as APOE in open-access papers (continued):
Sharing a sentence is not in itself a finding about the gene and the disease.
tumor (continued). "Likewise, apolipoprotein E was up-regulated both in serum and tumour samples, the ratio HCC/control being 2.2 and 3.9, respectively." (PMID 25872475, 2015). "APOE may be involved in signal transduction and lipid transport essential for proliferation and survival of tumor cells or may potentiate tumor proliferation and survival maintaining a specific microenvironment." (PMID 25741405, 2015). "Furthermore, patients with high APOE tumor expression had a shorter survival than those with low APOE expression." (PMID 25428203, 2014). "Although further investigation into the anti-angiogenic tumor properties of APOE is required in different cancer models, these results pose interesting theories regarding the pharmacological anti-angiogenic activity of APOE." (PMID 25428203, 2014). "Complement C3 may be used as a marker for the diagnosis of early-stage PC, while complement C4b1 and apoE are closely correlated with tumor development, reflecting the biological behavior of PC, and thus may be used as diagnostic markers of advanced PC." (PMID 23946775, 2013). "ApoE binds heparin and proteoglycans with very high affinity and inhibits proliferation of several cell types such as: endothelial cells, lymphocytes, smooth muscle cells, and several types of tumour cells." (PMID 19455140, 2009). "However, there was also increased APOE expression in the tumor core." (PMID 40745073, 2026). "Those APOE may be secreted either by tumor cells or macrophages." (PMID 40745073, 2026). "In this study, APOE was also associated with CD68 in the tumor core but not the tumor edge." (PMID 40745073, 2026). "However, the effect exerted by APOE within tumor immune regulation, especially in AEG TME, remains unclear." (PMID 40963562, 2025). "In addition, we found APOE+ macrophage might be the terminal cells which indicated tumor might promote macrophage to polarized in the direction of APOE+ macrophage under some extent signaling." (PMID 40303328, 2025). "Moreover, the observed inhibition of tumour growth in vitro and in vivo by APOE overexpression supports the hypothesis that APOE may play a tumour‐suppressive role." (PMID 39810624, 2025). "The results indicate that Macro_APOE/CTSZ plays a substantial role in the immune dysfunction in higher‐grade tumor, and also assume a metabolic checkpoint of Macro_APOE/CTSZ, which may allow cells to return to antitumor phenotype by targeting pathway of glutamate to glutamine." (PMID 36587392, 2023). "Apolipoprotein E (Apo E) can mediate cholesterol metabolism and may enhance or inhibit the immune response under different circumstances, so targeting Apo E can be regarded as a direction of tumor immunotherapy." (PMID 38264667, 2023). "Therefore, we aimed to investigate the role of APOE polymorphisms on the tumor with or without CVD in southern China." (PMID 36057714, 2022). "As a consequence, since ApoE internalization is crucial for cancer cell development, it might be speculated that this interaction could be the basis of nanoparticle-boosted uptake in tumor cells." (PMID 36235232, 2022). "Further studies reveal that apoE KO mice have less orthotopic mammary tumor development and pulmonary metastasis than wild type (WT) mice and lung tumor development and metastasis are suppressed through enhancing anti-tumor activity of natural killer (NK) cells." (PMID 36341364, 2022). "The decrease in APOE expression may promote tumor metastasis through NOTCH1, HIF1A, and TGFB1." (PMID 36428687, 2022). "During the malignancy development of hepatocytes, cadmium can enhance the DNA methylation of the ApoE promoter region and prevent the action of the transcriptional regulator of ApoE called LXRα, thus downregulating the expression of ApoE and leading to tumor invasion." (PMID 36506554, 2022). "Thus, APOE activated immunity in the tumor microenvironment." (PMID 34249502, 2021).
tumor (continued). "Furthermore, DC_c1 cells might have functional alteration and enhanced lipid utilization due to the remodeling of TME as the increased expression of CXCL9, IDO2, APOA2, and APOE compared to their non-tumor counterparts." (PMID 33298893, 2020). "Thus, the tumor growth and metastasis were compared in WT and ApoE knockout (KO) mice." (PMID 31275318, 2019). "Thus, we investigated whether CD8α T cells and NK cells are involved in tumor growth inhibition in ApoE KO mice." (PMID 31275318, 2019). "However, little is known about the effect of external ApoE on tumor cells." (PMID 29567987, 2018). "Mechanism studies revealed the disrupted tight junction, reduced P‐glycoprotein expression and ApoE‐dependent PS‐80 permeation collectively contribute to the enhanced drug delivery, resulting in significantly stronger antitumour efficacy and longer survival time in the tumour‐bearing mice." (PMID 29956460, 2018). "In addition, APOE has been shown to be a potent inhibitor of the proliferation of several cell types and may be effective in modulating angiogenesis and tumor cell growth." (PMID 25428203, 2014). "These exosomes deliver apolipoprotein E (ApoE) to cancer cells that make them undetectable by downregulation of MHC-I expression and inhibition of tumor-intrinsic immunogenicity." (PMID 41294803, 2025). "More importantly, previous study has demonstrated that LXR/ApoE axis impairs the viability of MDSCs through LRP8, thus facilitating anti-tumor immunity by activating cytotoxic T lymphocytes (CTLs)." (PMID 39972392, 2025). "To further investigate the transcriptional and genomic alterations of APOE+ macrophage marker genes in LUAD, we first compared their expression profiles between TCGA tumour samples and GTEx normal lung tissues." (PMID 40736341, 2025). "We thereby established a correlative CCI network and identified strong interactions between tumor cells and Fbs that were CD34+, MMP3+, or APOE+." (PMID 40126353, 2025). "Using CellTrek, we directly visualized the communication networks between APOE− and APOE+ tumour cells and immune cells on histological slides." (PMID 39810624, 2025). "In the vicinity of the tumor, these APOE+ macrophages shape immunosuppressive TME by releasing abundant TGF-β signals, limiting anti-tumor effector T cells activity in ICB-resistant tumors, and contributing to tumor progression." (PMID 40303328, 2025). "The CellTrek mapping analyses effectively visualized the spatial distribution of SPP1+ TAM, STMN2+ TAM, APOE+ TAM, Tregs, CD8+ Tex cells, and Tem/Teffe cells within tumor sections, revealing their substantial infiltration in TIME." (PMID 41438751, 2025). "By secreting specific cytokines and chemokines such as CCL2, ApoE, and TIMP1, it promotes the invasion and metastasis of tumor cells." (PMID 40495209, 2025). "The LXR/ApoE axis influences MDSC survival, and LXR agonists (RGX-104/GW3965) have demonstrated efficacy in mouse models, significantly reducing tumor growth and metastasis by inducing MDSC apoptosis." (PMID 40607438, 2025). "In summary, APOE promotes the proliferation, tumorigenic potential, migration and invasion capabilities of PTC cells by regulating the tumour immune microenvironment." (PMID 39810624, 2025). "M2 MDEs can transport ApoE, which interferes with the ATPase activity of binding immunoglobulin protein (BiP), which reduces MHC-I expression on tumor cells and inhibits the ability of CD8+ T cells to exert cytotoxic effects on these cells." (PMID 40612677, 2025). "Overall, these results demonstrated that spermine induce immunosuppressive TME through promoting Macro_APOE polarization, and inhibiting cytotoxic CD8+T infiltration, ultimately facilitating tumor progression." (PMID 40963562, 2025). "We further performed immunohistochemical analysis to assess APOE and ABCA1 expression in tumour tissues." (PMID 39810624, 2025).
tumor (continued). "Subsequently, upon separately knocking down APOE and SCRRB1 in BON1, we observed a significant reduction in the number of lipid droplets induced by TMZ, as well as an increase in sensitivity of the tumor to TMZ." (PMID 41390817, 2025). "Suppression of FTO significantly stabilizes apolipoprotein E (APOE) mRNA and coordinates with IGF2BP2, leading to the promotion of GLUT1 expression and tumor glycolysis by modulating the IL-6/JAK2/STAT3 signaling pathway." (PMID 41373022, 2025). "Reduced APOE expression activates the FAK/ERK/MMP pathway, enhancing cell invasiveness and tumor progression." (PMID 40535817, 2025). "This is consistent with a previous report which has demonstrated that LXR/ApoE axis represses MDSCs viability in dependent of LRP8, thereby activating CD8+ T cells and facilitating anti-tumor immunity." (PMID 39972392, 2025). "The interruption of APOE-mediated lipid uptake via a SCARB1 inhibitor named as block lipid transport-1 (BLT-1), suppressed TMZ-induced HRR activation and sensitized tumor cells to TMZ treatment in preclinical models, including PDCs, PDOs, and PDXs." (PMID 41390817, 2025). "In future work, we plan to extend our research by incorporating animal models to experimentally validate the interactions between CD14+APOE+ cells and MMP7+ tumour cells." (PMID 39187937, 2024). "Immunosuppressive cluster C5, which highly expresses C1QA, APOE and RNASE1, was at the terminal state of differentiation and played an important role in the formation of an immunosuppressive tumor microenvironment." (PMID 38408082, 2024). "The demethylase FTO has been shown to be responsible for decreasing m6A methylation of Apolipoprotein E (APOE) mRNA and modulating the IL-6/JAK2/STAT3 signaling pathway, thereby inhibiting tumor glycolysis and abrogating tumor growth." (PMID 38902779, 2024). "In an immunotherapy cohort from the ORIENT‐3 clinical trial, NSCLC patients who responded unfavourably exhibited higher infiltration of CD14+APOE+ cells and MMP7+ tumour cells." (PMID 39187937, 2024). "First, further validation in independent cohorts and prospective studies is necessary to confirm clinical utility of CD14+APOE+ cells and MMP7+ tumour cells." (PMID 39187937, 2024). "It has been demonstrated that APOE plays a role in regulating the abundance of MDSC and anti-tumor immunity." (PMID 38685045, 2024). "We compared proportions of each myeloid subtype in each patient, finding that SPP1+APOE+ TAM (Diff = 9.5%, p = 0.011) and CD62L+IFN-high neutrophils (Diff = 5.0%, p = 0.046) were significantly enriched in primary tumor patients versus adjacent normal." (PMID 39075108, 2024). "Functional investigations have demonstrated that exosomes generated from M2 macrophages transfer APOE to cancer cells, resulting in the reduction of MHC‐I expression and inhibition of the tumour's inherent ability to provoke an immune response." (PMID 39187937, 2024). "In tumours, both AMɸ and AIMɸ upregulated genes involved in cholesterol and lipid transport and metabolism (such as ABCA1, APOC1, APOE, FABP3 and FABP5) compared to the background tissue." (PMID 38782901, 2024). "Accumulated evidence revealed that LAMs shared a high expression of typical genes (such as APOE, APOC1, GPNMB, TREM2, SPP1 etc.)and played a central role in tumor immunity." (PMID 38346944, 2024). "Compared to those in normal tissues, APOE, STEAP4, and C1QTNF3 expressions were upregulated in tumor tissues, whereas BNIP3L and PPARGC1A expressions were downregulated." (PMID 39524226, 2024). "In terms of tumor formation, the SKH-hr2+ApoE model again showed the highest mean (M = 0.850), while the SKH-hr1 model had the lowest mean (M = 0.183)." (PMID 39456640, 2024). "We particularly observed relationships with SIGLEC + macrophages, LAM2 APOE + macrophages, and EGR1 + macrophages, which are analogous to M2-like, tumor-promoting, macrophages." (PMID 39529126, 2024).
tumor (continued). "We observed that CD14+APOE+ cells were prominently represented in samples with immune exclusion, exhibiting a strong correlation with MMP7+ tumour cells." (PMID 39187937, 2024). "We then identified cells exhibiting positive staining for specific markers, including PanCK (tumour marker), CD14 and APOE." (PMID 39187937, 2024). "The spatial co‐location of CD14+APOE+ cells and MMP7+ tumour cells was observed in ST data and further validated through multiplex immunofluorescence analysis conducted on 20 NSCLC samples." (PMID 39187937, 2024). "Binding of ApoE, one of the functional ligands of LILRB4, is coupled with T-cell suppression and tumor infiltration through LILRB4-mediated downstream signaling in AML cells." (PMID 38235377, 2024). "To summarise, our study provides insights into the composition of immune cells within tumours in NSCLC and emphasises the presence of CD14+APOE+ cells and MMP7+ tumour cells in close proximity as significant factors in immune exclusion." (PMID 39187937, 2024). "This study identified immune exclusion and activation patterns in NSCLC and the co‐location of CD14+APOE+ cells and MMP7+ tumour cells as contributors to immune resistance." (PMID 39187937, 2024). "WB analysis of serum and tumor tissue specimens confirmed the upregulation of eight proteins: APOA1, HBB, CAH1, HBD, LPA, SAA4, PF4V1, and APOE." (PMID 39194522, 2024). "Subsequently, we assessed the capacity of tumour cells expressing MMP7 and CD14+ cells expressing APOE to forecast the effectiveness of treatment in patients undergoing immunotherapy." (PMID 39187937, 2024). "Our findings align with the transcriptomics study, as we detected the presence of MMP7+ tumour cells and CD14+APOE+ cells in the NSCLC tumour region." (PMID 39187937, 2024). "The cell‒cell communication between MMP7+ tumour cells and CD14+APOE+ cells was consistent with the results based on the ST data." (PMID 39187937, 2024). "ApoE can mediate inflammation and immune responses in the TME, stimulate angiogenesis, and participate in tumor progression, proliferation, and metastasis." (PMID 38349474, 2024). "The combination therapy downregulated immune response suppressors such as ApoE, CD69 and Cxcr4, which altered the transcriptome of CD11b+ cells to restore their anti-tumor function." (PMID 39239650, 2024). "Experimental validation, such as functional assays or in vivo models, is required to definitively establish the mechanistic interactions between CD14+APOE+ cells and MMP7+ tumour cells in promoting immunotherapy resistance." (PMID 39187937, 2024). "The co‐location of CD14+APOE+ cells and MMP7+ tumour cells was observed in both ST and bulk transcriptomics data, validated by multiplex immunofluorescence performed on 20 NSCLC samples." (PMID 39187937, 2024). "Glutamate‐to‐glutamine metabolic pathway and GLUL expression, specifically activated and overexpressed in Macro_APOE/CTSZ, were higher in high‐grade compared with low‐grade tumor samples." (PMID 36587392, 2023). "Nonetheless, SPP1, APOE, and TREM2 manifested more average fold changes than the C1Q genes and were expressed in more tumor cells than normal tissue cells." (PMID 37187751, 2023). "On the contrary, it has also been shown that APOE ablation (global knockout mice) increases CD8+ T cells and reduces tumor burden after implantation of KPC cells into the pancreas." (PMID 37958351, 2023). "Researchers have studied the role of ApoE in LXR-mediated MDSC deletion by analysing the effect of LXR treatment on tumour MDSC abundance and ApoE consumption in tumour cells after ApoE gene inactivation in stroma and immune system." (PMID 37261073, 2023). "The result showed that the gene expression of SLC3A1 and GLUL were highly expressed in Macro_APOE/CTSZ compared with other cell types in CRC and LC, and were upregulated in macrophage derived from tumor than normal tissues in CRC." (PMID 36587392, 2023).
tumor (continued). "Intriguingly, a chemical agonist LXR-mediated the activation of ApoE secretion devastates MDSC survival by facilitating the binding of ApoE to its receptor LRP8, resulting in a fortified anti-tumor response." (PMID 37124622, 2023). "The expression of APOE and SPP1 has been detected in macrophages during tumor progression, with SPP1 becoming highly expressed in lipid-associated macrophages." (PMID 37762157, 2023). "The identified TYROBP→TREM2→A2M→APOE→APOC1 cascade is supported by the reports that TREM2 is expressed in tumor macrophages in over 200 human cancer cases and that there are interactions between TREM2/A2M, TREM2/APOE, A2M/APOE, and APOE/APOC1." (PMID 37129360, 2023). "Comparison of the gene expression of TREM2+ TAMs between the tumor and adjacent normal tissue revealed that TREM2, SPP1, APOE, C1QA, C1QB, and C1QC were upregulated in tumors, which was consistent with the results for GSE160269." (PMID 37187751, 2023). "At first, tumor cells were shown to interact with TAM subtypes, such as the ANXA1-FPR3, PLAU-PLAUR, and MDK-LRP1 pairs between the Ductal_cell_A and Macro_SPP1_APOE cell types in PDAC." (PMID 38002057, 2023). "Since macrophage APOE (Apolipoprotein E) is tumor promoting, we performed co-immunofluorescent staining for APOE, F4/80, and ECAD and detected a reduction in APOE expression." (PMID 36727849, 2023). "We found a high correlation of APOE, LGALS1, and PCSK1N, which were primarily expressed in SLS tumor cells, with macrophage frequency/activity in SLS-dominant tumors." (PMID 36028490, 2022). "Since APOE was expressed in nearly 90% of TAMs, we focused on SPP1+ TAMs and found more interactions of CAFEndMT with SPP1+ TAMs than that with SPP1- TAMs in tumor samples." (PMID 36333338, 2022). "To further analyze the significance of the findings here in human tumors, we investigated APOE, PD-1 and TIGIT protein expressions from 30 human tumor specimens by using immunohistochemistry." (PMID 36147474, 2022). "Binary logistic regression revealed that ApoE ε3/ε3 and ε3/ε4 have an opposite effect on the development of LSCC in terms of the degree of tumor differentiation." (PMID 35892323, 2022). "Protein Atlas verified that APOE, MIF, and NR3C1 were expressed in tumor tissues at different levels." (PMID 36452480, 2022). "Mass spectrometric analysis has shown the existence of apolipoprotein E (ApoE) within the exosomes, activating the PI3K-AKT pathway and inducing epithelial-mesenchymal transition (EMT), increasing tumor metastasis potential." (PMID 35646915, 2022). "The results show that targeting apoE in both the tumor cells and the host (apoE-/- B16 cells injected into apoE-/- C57/BL6 mice) results in delayed tumor growth, and significant rejection of tumor cell inoculation with improved overall survival." (PMID 36341364, 2022). "Tumor growth was also impaired when apoE-/- B16 cells were injected into lrp8-/- mice, suggesting apoE/LRP8 receptor engagement is important in mediating the apoE protective effect on tumor growth." (PMID 36341364, 2022). "Among the six TAM clusters, MHC-II TAM (cluster 14) highly expressed HLA-DRB5, APOE, and APOC1, and was more enriched in tumor core than in tumor-normal interface." (PMID 36423636, 2022). "A recent study showed that ApoA or ApoE stimulated tumor growth in MCF-7 cells (ER-positive cells) and inhibit tumor ability in MDA-MB-231 cells (ER-negative cells)." (PMID 35986413, 2022). "We validated the transcriptional expression of identified 6 key fibrosis factors (PCOLCE2, APOD, APOE, TIMP1, HTRA3 and MT1A) in tumor and normal tissues obtained from 20 PTC patients." (PMID 36387901, 2022). "The protein activity of the C1Q family of proteins, APOE, and TREM-2 was significantly upregulated in macrophages in tumors compared to non-tumor tissues." (PMID 34831009, 2021). "Pre-analysis centrifugation of samples spiked with the T24 tumor cell line reduced levels of MMP9, SDC1, PAI1, ApoE, and ANG." (PMID 34204951, 2021).